CD4 (CD4 molecule)
Diseases named in the same sentence as CD4 in open-access papers (continued):
Sharing a sentence is not in itself a finding about the gene and the disease.
infection (continued). "The intestinal mucosal tissue is the initial site of HIV replication and acute phase of infection is associated with the vast depletion of CD4+ T cells in the gut due to either direct killing by the virus, or due to CD4+ T cells apoptosis." (PMID 28326084, 2017). "In multiple models of infection the loss of the IL-27Rα has been associated with CD4+ T cell-mediated immunopathology linked with the overproduction of IFN-γ." (PMID 28129374, 2017). "A study utilizing coculture of autologous activated CD4+ T lymphocytes with SAMHD1-deficient MDDCs infected with primary clinical HIV-1 isolates indicated enhancement of both infection and IFN response." (PMID 29176984, 2017). "Accordingly, Il18r1−/− mice display lower levels of Th1 cells and are highly susceptible to infection, but can be rescued from mortality by the adoptive transfer of WT CD4+ T cells." (PMID 28895840, 2017). "It is known that the decline of CD4+ T lymphocytes causes the HIV-infected person to become highly susceptible to various infections including the wide range of opportunistic oral manifestations." (PMID 28326084, 2017). "RNA interference (RNAi) was performed to study the loss of function of these genes in HIV‐1 trans‐infection from DCs to CD4+ T cells." (PMID 28923824, 2017). "The effect of infection of these cells in secondary lymphoid tissue via CCR5 is in distinct contrast to the massive depletion of CD4+ T cells in mucosa-associated lymphoid tissue." (PMID 28484447, 2017). "One possible mechanism underlying the failure to prime naïve CD4 T cells in this mouse model is the rapid clearance of antigen that occurs following this heterosubtypic infection." (PMID 28493882, 2017). "Nevertheless, we clearly demonstrated here that Il18r1−/− mice display low levels of IFN-γ+CD4+ T cells in response to infection with T. cruzi and are highly susceptible to infection." (PMID 28895840, 2017). "AIDS affects more than 35 million people worldwide and the virus causes lytic infection of immune cells, primarily CD4+ lymphocytes." (PMID 29354120, 2017). "Upregulated IP-10 in HIV infections is associated with high inflammation levels, rapid loss of CD4+ T cells, promoting infection by enabling viral reservoirs." (PMID 28955339, 2017). "If the relative level of CD4 expression on HSPCs determined susceptibility of HSPCs to infection, then CD4 expression would serve as an indicator of the subtypes of HSPCs potentially targeted by HIV." (PMID 28732051, 2017). "In this animal model, the depletion of CD4+ T cells during the early stage of infection resulted in significantly fewer NK cells in the lung tissue as compared with CD4+ T intact mice, which was associated with a higher pathogen load in the lungs." (PMID 29371543, 2017). "The enhanced susceptibility of C3H/HeN mice to the infection with R. conorii compared to C57BL/6 mice has been connected to the reduced ability of DCs to induce IFNγ-producing CD4+ T cells." (PMID 28770333, 2017). "Depletion of CD4+ T cells in IL-27Rα-/- mice led to a decrease in AAMs and reduced weight loss after infection, while eliminating STAT6 signaling in IL-27-deficient mice reduced Th2 responses and decreased mortality." (PMID 28129374, 2017). "Antibody-deficient mice depleted of CD4+ T cells are incapable of resolving secondary infection naturally because they are deficient in both protective arms (humoral and cellular) of antichlamydial immunity (9, 11, –, 13)." (PMID 28739831, 2017). "Low-level cell-associated HIV RNA (3.2 copies/million CD4+ T cells) was detected 32 days after infection." (PMID 28953320, 2017). "Unexpectedly, the number of classical CD4+Foxp3+ Tregs producing IL-10 was similar in the cardiac tissue of Ebi3-deficient and WT mice at day 15 after infection, suggesting that Ebi3 was unable to promote the development of classical Tregs." (PMID 29033934, 2017).
infection (continued). "We found increased number of IFN-γ producing CD4+ T cells in the cardiac tissue and spleen of Ebi3-deficient mice compared to WT counterparts 15 days after T. cruzi-infection." (PMID 29033934, 2017). "Even with high numbers of CD4+ cells, early after infection, HIV patients are at increased risk of TB, though that disease is largely confined to the lung." (PMID 29259086, 2017). "Cytotoxicity by CD4 CTL becomes more effective when CD8 CTL activity is impaired during infections in association with virus escape strategies." (PMID 28280496, 2017). "Studies in experimental VL in mice, caused by infection with the human parasites L. donovani or L. infantum, show the development of antiparasitic IFNγ-producing, Tbet+ CD4+ T (Th1) cells is critical for resistance against infection." (PMID 29167671, 2017). "CD4+ T cells from these DC-depleted mice exhibited reduced proliferative activity associated with diminished IFN-γ production at day 4 post infection." (PMID 29085373, 2017). "In the multiple logistic regression analysis, the only significant risk factor for infection by oncogenic HPV was CD4 nadir <200 cells/μL (OR: 3.66; 95% CI 1.05–12.75)." (PMID 28953633, 2017). "The infection caused depletion of CD4+ T cells on days 1 and 3 post infection, but on the fourth day, NDV AF2240 caused the CD4+ cell number to increase to 1.46 × 105 from the initial 0.79 × 105 cells while NDV IBS002 increased the number to 1.08 × 105 cells." (PMID 28569155, 2017). "In this study, we demonstrated that although the number of all cell populations decreased dramatically after infection, the most significant effect is on the immature CD4+CD8+ thymocyte population caused by apoptosis." (PMID 27733201, 2016). "When analyzed at 3 weeks post infection, we found R3A-5/6AA was significantly less pathogenic than R3A in vivo, with reduced CD4 T cell depletion in the blood, spleen and bone marrow." (PMID 27026376, 2016). "The model contains two subpopulations of target cells (CD4+ T cells) with lower and higher susceptibilities to infection due to different level of co-receptor expression." (PMID 27668463, 2016). "It is plausible that the amount of initial antigen exposure controls the extent of differentiation and that vaccinated animals were more capable of containing the infection initially, preventing the loss of CD4 polyfunctional capacity." (PMID 27799930, 2016). "Intriguingly, we noted that the strongest correlation to reduced %CD4+ T cells in HIV-2 aviremic infection was linked more to accumulation of PD-1+ and less to CD38+HLA-DR+ cells." (PMID 27525551, 2016). "Specifically, development of neutralization breadth was associated with increased frequencies of PD-1+CD4+ T cells in early infection, and with higher frequencies of class-switched antibodies in co-cultures of CXCR5+CD4+ T and B cells." (PMID 27938646, 2016). "In this regards, IL-15 SA caused a substantially higher activation of CD4+ T cells (~ 55% CD69 expression) post infection as compared to the sham (~10%) and vehicle treated burn wound infected group (~32%)." (PMID 26859674, 2016). "For example, Wei and Tabel showed that depletion of CD4+CD25+Foxp3+ T cells by anti-CD25 mAb leads to complete control of infection in highly susceptible BALB/c mice." (PMID 27242788, 2016). "Pneumonia due to the opportunistic human fungal pathogen Pneumocystis jirovecii is an AIDS-defining illness, and there is a direct inverse relationship between CD4+ T-cell counts in the blood and the risk for infection." (PMID 27242785, 2016). "During long-term infection, loss of CD4+ T cells compromises immune control, leading to recrudescence in the lungs, progressive pathology, and death." (PMID 27582728, 2016). "We have recently shown that Vpu is closely associated with the down-modulation of CD4 molecules from the infected cells during the acute phase of infection in vivo." (PMID 27086687, 2016).
infection (continued). "Conversely, a strong and broadly directed CD4+ T cell response to HCV has been associated with spontaneous clearance of infection." (PMID 27362419, 2016). "To evaluate this, we compared the “functional avidity” of CD4 T cells specific for these epitopes when elicited by infection vs. when encoded in MalE." (PMID 27329272, 2016). "Subsequent challenge of high-dose SIVmac251 resulted in infection in all animals; however, the acute phase of infection showed a reduction in viral replication by more than two orders of magnitude and protection against CD4 T cell (CD28+ CD95+) loss." (PMID 27446074, 2016). "En analyse univariée, les FDR de décès étaient la durée de l’infection < 12 mois, le taux de CD4 au moment du diagnostic < 200/mm3, le nadir CD4 <50/mm3, les antécédent(s) d’IO, la durée de la TAR < 12 mois et le tabac." (PMID 28292068, 2016). "Hypothetically, our data showing a decline in the content of IL-17 in BAL CD4+ T cells from smokers illustrate a feasible mechanistic explanation for bacterial colonization and increased susceptibility to infection in the lungs of smokers." (PMID 27798682, 2016). "The response of T cells, and particularly CD4+ T cells, is important during infection with pathogenic Neisseria as these cells are involved in directing the magnitude and quality of humoral immune response." (PMID 27111850, 2016). "An expanded CD4 + CD28null cell population in this study was associated with an increased risk of infection and increased mortality in patients with AAV." (PMID 27450392, 2016). "Strikingly, elevated IP-10 levels before infection were associated with rapid progression (OR = 3.24 p = 0.01), CD4+ T-cell counts falling below 350/mm3 more rapidly in individuals with pre-infection IP-10 levels above the median." (PMID 27509048, 2016). "In HCV infection, T cell responses are critical in controlling infection, as evidenced by class I and II HLA associations, CD4+ and CD8+ depletion experiments in the chimpanzee model and functional assays during early HCV infection." (PMID 27092143, 2016). "Consistent with this, WSX-1/IL-27 was recently demonstrated to have a critical role in limiting the effector CD4+ T-cell-mediated immunopathology caused by IL-12-dependent IFN-γ production during infection with lethal P. berghei NK65." (PMID 26991425, 2016). "Taken together, this suggests that infection with HIV harboring a key A*24:02-restricted Nef escape mutation is associated with significantly poorer long-term CD4 outcomes in A*24:02-expressing individuals." (PMID 26953793, 2016). "In humanized mice, R3A infection caused rapid depletion of both infected and uninfected CD4 T cells." (PMID 27026376, 2016). "Cell-mediated immunity was not investigated during this trial but for Salmonella in poultry, susceptibility to the infection is correlated with a fall in CD4+ and CD8+ T-lymphocytes and γδ T-lymphocytes in the oviduct, and with T-lymphocyte hyporesponsiveness." (PMID 27519174, 2016). "A putative and somewhat contradictory role of CD4+Foxp3+ Tregs has been demonstrated in various models of pathogenic infections." (PMID 27439902, 2016). "Conversely, these cells downregulate CD28 expression, which is consistent with previous observations that CD4+CD28− T cells are associated with enhanced cytotoxic functions following infections with CMV and hepatitis B virus (HBV)." (PMID 28003809, 2016). "Multidimensional clustering bioinformatic tools were used to identify CD4+ T-cell subpopulations linked to infection type and disease stage." (PMID 27525551, 2016). "Memory CD4 T cells generated by live infection retain some of the differentiation-associated changes attained during the effector phase of the response." (PMID 27148257, 2016). "Burn and infection caused a remarkable decline in circulating lymphocyte counts and a decrease in spleen CD4+ and CD8+ T cells on day 2 after infection." (PMID 26859674, 2016).
infection (continued). "This situation is similar to the infection of CD4+ T cell-deficient C57BL/6 MHCII-/- mice with R. typhi where CD8+ T cells are present and can compensate for the absence of CD4+ T cells." (PMID 27875529, 2016). "A low CD4+T-cell count at entry was a risk factor fortype-specific, re-infection, or HPV DNA persistence." (PMID 26872340, 2016). "Infection of Lyz2creKlf2fl/fl mice was associated with increased numbers of IL-4GFP+ CD4+ T cells in the lungs and an elevated IL-4GFP mean fluorescence intensity (MFI)." (PMID 27302755, 2016). "This has been demonstrated in follow up analyses of the RV144 case-control data, where poly-functionality in CD4+ ENV-specific T cells was shown to be inversely correlated with infection risk." (PMID 27077384, 2016). "Viral persistence results from long-lived reservoirs that include memory CD4 T cells and perhaps other cell types that are established early after infection in humans and, in pathogenic models of SIV infection in nonhuman primates." (PMID 27855210, 2016). "It is possible that this increased risk of HIV-1 acquisition, and the more rapid CD4+ T-cells loss observed here in individuals with higher IP-10 levels before infection, is due to IP-10 enhancement of the infection." (PMID 27509048, 2016). "These parasites with the exception of hookworm take advantage of the low CD4+ T thus causing infection in these patients." (PMID 26754404, 2016). "Using this model, we found that rectal HSV-2 infection increases the frequency of α4β7high CD4+ T cells in the rectal tissue, which is associated with increased susceptibility to rectal SIVmac239wt infection." (PMID 26886938, 2016). "Like previously reported, we used quantitative PCR to quantify cell-associated HIV load in sorted Ag-specific CD4 cells as an indication of their natural infection history." (PMID 27280548, 2016). "Since morphine conditioning results in a higher steady state level of target cells in the Th compartment, which have a higher infection rate, morphine was expected to cause a greater loss of CD4 cells." (PMID 27668463, 2016). "Our finding that depletion of CD4+ T cells during the immunization phase results in a loss of protection against lethal challenge infection further indicates the need for T cell help in mounting a protective neutralizing antibody response." (PMID 27336830, 2016). "Surprisingly, DC are more susceptible to in vitro infection with viral biofilms than autologous CD4+ T-cells, underlining their potential importance in virus dissemination." (PMID 27005656, 2016). "A similar pattern of association between CD4+ T cell cytokine production and Blimp-1 expression was found in mice with experimental VL caused by infection with the human protozoan parasite L. donovani." (PMID 26765224, 2016). "Env is a 3-kb HIV gene that encodes the envelope glycoprotein, which triggers infection by binding CD4 and a co-receptor (either CXCR4 or CCR5) and is the primary target for HIV vaccine development." (PMID 26789840, 2016). "Minimizing inflammation is important because activated CD4+ T cells are much more susceptible to infection than resting T cells." (PMID 26807859, 2016). "Group 1 comprised children with low CD4+ T-cell counts and high clinical event rates, reflecting the well-recognized infection risk among children with profound immunosuppression." (PMID 27190179, 2016). "We used a primary activated PBMC culture infection model to study the pathogenesis of the highly pathogenic dual-tropic HIV-1 strain (termed R3A) on CD4 T cells." (PMID 27026376, 2016). "Broad neutralization was associated with high viral load, low CD4+ T cell counts, virus subtype C infection and HLA*A3(-) genotype." (PMID 26766578, 2016). "More importantly, we provided direct evidence, that infection-associated IL-27 signaling served to extend the survival of the infected host by dampening CD4+ T cell activation and their secretion of IFN-γ." (PMID 26222157, 2015).
infection (continued). "Infection by more than one high-risk type was strongly associated with abnormal cytology, even after adjusting for age, CD4+ lymphocyte count, and specific high-risk HPV types." (PMID 26100400, 2015). "cDCs and CD4+ T cells in the spleen were analyzed on day 3 post-infection to determine if the cause of the attenuated expression of CXCR3 on CD4+ T cells was due to an early defect in activation or to impaired differentiation." (PMID 25768944, 2015). "Infection by human immunodeficiency virus-1 (HIV-1) is associated with a progressive decrease in CD4 T-cell numbers and the consequent collapse of host immune defenses." (PMID 26247731, 2015). "There were clear changes associated with long-term infection including a reduction in % FoxP3± regulatory CD4± T cells within the lamina propria and % T-bet± Th1 cells in the epithelium." (PMID 25938477, 2015). "Th17-type CD4+ T-cell responses and cytokines appear to play a protective role, whilst Th2-type responses are associated with impaired control of infection and poor outcomes." (PMID 25853653, 2015). "Given that CD4+ T-cell loss is thought to be linked to immune activation in pathogenic infections, the relatively low levels of chronic immune activation seen in these captive animals most likely explains why CD4+ T-cell loss is only a gradual process." (PMID 26360709, 2015). "This virus strain was also able to infect primary CD4+ T cells and this infection was associated with a decrease in their proliferation." (PMID 26084511, 2015). "Using our model, we show that direct infection of resting CD4+ T cells with wild-type viruses leads to loss of surface CD4." (PMID 26537682, 2015). "CD4 T cells expressing the chemokine receptor CCR5 are the predominant targets of HIV during initial infection, and specific CD4+ T helper (Th) subsets are particularly susceptible to HIV." (PMID 26335139, 2015). "Because of an increased risk of infection by these viruses among IDUs, we assessed the level of CD4 T-cells in blood and compared these between IDUs receiving anti-HIV medications and those naïve to ART, as well as between genders and infection status." (PMID 26208212, 2015). "HIV/SIV infection causes rapid depletion of CCR5+CD4+ T cells by 21 days after infection and most infected cells in the intestine are present in immune inductive sites." (PMID 26167159, 2015). "Th17 CD4+ T cells (producing IL-17) have also been implicated in control of this infection, particularly in the early phases." (PMID 25611466, 2015). "In summary, this study shows that infection with S. haematobium is associated with alterations of the frequency and activity of CD4+CD25hiFOXP3+ regulatory T cells and that these in turn affect proliferation and global cytokine responses." (PMID 26291831, 2015). "M3R deficiency significantly abrogated the ability of BALB/c mice to launch an effective adaptive immune response to primary and secondary infection, and underlying this defect were reduced CD4 T cell-associated protective cytokine responses." (PMID 25629518, 2015). "To dissect which viral proteins contributed to the loss of surface CD4 in our system, we performed infections of resting cells with either wild-type 89.6 virus or 89.6 viruses lacking vpu, nef, or env." (PMID 26537682, 2015). "In this study, we investigated the contribution of signalling through the M3R to protective immunity against N. brasiliensis, using both infection of M3R gene deficient mice (M3R−/− mice) and ex vivo CD4 T cell assays." (PMID 25629518, 2015). "Surprisingly, however, limited studies have examined in detail either the loss or repopulation of CD4+ T cells during infection and therapy or characterized the nature of CD4+ T cells resident in the oral mucosa relative to other mucosal tissues." (PMID 26065003, 2015). "It has been shown that the presence of X4/dual mixed viruses is associated with a more rapid progression of the infection and CD4 lymphocyte loss." (PMID 26297538, 2015).